INS (insulin)
Diseases named in the same sentence as INS in open-access papers (continued):
Sharing a sentence is not in itself a finding about the gene and the disease.
Obesity (continued). "For instance, HDAC11 deletion in mice prevented obesity after HFD feeding, and significantly improves insulin sensitivity and glucose tolerance." (PMID 39109269, 2024). "P. distasonis was negatively correlated with indicators of obesity such as body weights, glucose, ALT, AST, TG, TC, LDL‐C, NEFA, and insulin." (PMID 39687780, 2024). "Insulin, leptin, the renin-angiotensin-aldosterone system (RAAS), sodium excretion, and stress natriuresis were some of the mechanisms by which obesity raised blood pressure." (PMID 38887608, 2024). "Plasma lactate is increased in patients with obesity, metabolic syndrome, or T2DM and is inversely correlated with insulin sensitivity." (PMID 38788527, 2024). "Subsequently, GIP was shown to improve insulin sensitivity and reduce food intake, actions supporting the development of GIP-based multiagonists for the treatment of people with T2D and obesity." (PMID 39723966, 2024). "Each model focuses on a specific aspect of obesity: neural control and calories (EBM); carbohydrates and insulin (CIM); metabolic oxidation-reduction mismatches (REDOX); and developmental exposures to environmental stimuli (OBS)." (PMID 38212644, 2024). "Global genetic deletion of Hdac9 resulted in reduced weight gain, improved glucose tolerance and insulin sensitivity, and reduced ectopic lipid accumulation in high fat fed-mice, suggesting that HDAC9 plays a key role in obesity-related metabolic disease." (PMID 38672510, 2024). "The study, which included a relatively large number of people with severe obesity, supported previous evidence of BMI correlating negatively with fasting PYY and positively with fasting insulin." (PMID 38490484, 2024). "Participants with an HSI of >36 had significantly higher values for obesity-related parameters, including body weight, BMI, and WC, as well as elevated levels of FBG, HbA1c, TG, ALT, insulin resistance, and hs-CRP." (PMID 39408311, 2024). "In obesity studies, it has been shown that SIRT3 can act as a positive regulator of insulin sensitivity, while SIRT3 expression is down-regulated in obesity." (PMID 39458556, 2024). "Based on the evidence, TMAO can be a factor in the occurrence of obesity as well as the basis of obesity-related disorders such as body weight, BMI, and visceral fat index (VAI), and VAI itself can reduce insulin sensitivity." (PMID 38321994, 2024). "We included children and adolescents with obesity who completed an oral glucose tolerance test (OGTT, glucose + insulin) in the outpatient clinic." (PMID 38550917, 2024). "In addition, a well-established effect of AMPK activation is to enhance glucose uptake, which may explain the improvement in insulin action we observed in both lean individuals and individuals with severe obesity; however, this necessitates further investigation." (PMID 38324260, 2024). "These share a common root cause, and, therefore, explain why we see leptin and insulin rising where obesity may not, or may rise later on, meaning that obesity was not the first mover in causing the rises in these biomarkers associated with chronic metabolic diseases." (PMID 39062126, 2024). "The PCOS subgroup with obesity demonstrated notable increases in FBG levels and metabolism indicators, insulin and TG (P < 0.05)." (PMID 38600539, 2024). "The S+ was associated with increasing age, longer duration of T2DM, smoking and tobacco chewing, uncontrolled hypertension and T2DM, obesity, the presence of CKD, use of pioglitazone and insulin, and positive family history." (PMID 39606498, 2024). "Promisingly, in mouse models of obesity and diabetes, MOVA, 5OP and BHIBA have been shown to reduce adiposity, increase energy expenditure and improve glucose and insulin homeostasis." (PMID 39591977, 2024). "In this dataset of 205 participants spanning a wide BMI range, fasting GIP, insulin and PYY were shown to be important classifiers between participants with healthy BMI, overweight and obesity." (PMID 38490484, 2024).
Obesity (continued). "Sex, age, obesity, smoking, comorbidities, CCI and DCSI scores, OHA, insulin, statin, aspirin, immunosuppressants, influenza vaccination, adult health examination, HbA1C > 2 times per year." (PMID 39465742, 2024). "Interestingly, the WC animals had significantly higher levels of insulin compared to the LOb controls both at fasting and at 15 min during the glucose tolerance test, suggesting that a history of obesity may influence peripheral insulin sensitivity and/or beta cell function." (PMID 38961153, 2024). "With obesity, IR represents the most important trigger of MetS, thereby revealing the importance of GMP in improving tissue insulin sensitivity, decreasing adipogenesis and avoiding metabolic complications." (PMID 38542783, 2024). "The intake rhythm, appetitive measures, satiety hormones, insulin sensitivity, PPEE, and autonomic function of individuals with obesity were analyzed after a test meal composed only of UPF, compared to a meal without UPF but with similar foods." (PMID 39771019, 2024). "Expression of GLUT4 is regulated by the insulin signal pathway PI3K‐AKT and dysregulation of GLUT4 is reported to be involved in multiple CNS disorders like AD, Parkinson's disease and obesity‐related cognitive impairments." (PMID 39073013, 2024). "While obesity contributes to the development of SIBO by altering intestinal motility and promoting dysbiosis, it exacerbates MASLD through fat accumulation, insulin resistance, and other metabolic disruptions." (PMID 39742106, 2024). "It therefore seems likely that the metabolic effects induced by elevated plasma apelin concentrations in metabolic diseases such as obesity and T2DM are, at least initially, part of a compensatory mechanism to maintain functions such as insulin sensitivity." (PMID 39189510, 2024). "In mouse adipose tissue, nesfatin-1 expression and secretion increase with diet-induced obesity and are influenced by pro-inflammatory cytokines (IL-6, TNF-α) and insulin." (PMID 39455994, 2024). "In obesity-based IR, BITC enhanced insulin sensitivity in a Nrf2-dependent manner, lowering subsequent hyperglycemia in vivo and in vitro, potently offering protection against obese T2D." (PMID 39770075, 2024). "As mentioned in the obesity section, proteins like PLIN1 and CIDEC affect leptin production and insulin sensitivity." (PMID 39030618, 2024). "Teenage patients with PCOS and obesity compared to the control group had significantly higher HOMA-IR and lower insulin sensitivity according to WBISI (Whole body insulin sensitivity index)." (PMID 39415788, 2024). "Regular physical exercise improves insulin sensitivity and is the first-line approach to manage both reproductive and metabolic disturbances in those with PCOS and overweight or obesity, but adherence is low." (PMID 38180081, 2024). "Obese mice with the Ccr2−/− genotype show increased insulin sensitivity and greater glucose tolerance, which additionally indicates that CCR2 plays a role in regulating glucose levels in obesity." (PMID 39457105, 2024). "Therefore, the insulin signaling pathway may also provide a target in treating obesity." (PMID 38327997, 2024). "We demonstrated that the concentrations of fasting glucose and insulin, the HOMA-IR index and HbA1C were significantly higher in the participants with obesity than the other two groups." (PMID 39203787, 2024). "It has been reported that C57BL/6J mice are prone to obesity from an HFD and exhibit increased blood glucose levels and insulin resistance, making them suitable for creating a T2DM model." (PMID 39479116, 2024). "When T2DM and obesity were considered together, these patients (Obesity/T2DM) exhibited the highest HbA1c, HOMA-IR and fasting glucose, insulin, hsCRP and triglyceride levels (all p < 0.001)." (PMID 38755195, 2024).
Obesity (continued). "As the global obesity epidemic becomes a major driving force behind the increasing prevalence of T2DM, obtaining a method to enhance insulin sensitivity would have significant clinical application value." (PMID 39735643, 2024). "Following this strain investigation, in humans with obesity vs. non-obese insulin-resistant humans, the randomized administration of pasteurized Akkermansia muciniphila for three months was only slightly associated with loss of body weight, but improved insulin sensitivity was shown." (PMID 39594528, 2024). "Specifically, insulin increases SNA similarly in lean males and females, while this sympathoexcitatory response to insulin is amplified in males with obesity, it is abolished in females with obesity." (PMID 39000449, 2024). "This has clinical relevance, as both insulin and free IGF-1 levels are increased in individuals with obesity, and T cells have been found to dominate peripheral inflammation in obesity in human studies, with Th17 cells having a particularly prominent role." (PMID 38383709, 2024). "This may be because obesity and high fat intake could promote the intake of fatty acids and increase fatty acid metabolites in muscle cells, aggravate the inflammatory response of the body, interfere with insulin signaling pathway, raise blood sugar and aggravate IR." (PMID 38528483, 2024). "However, previous studies in mice have shown that increasing IR in obesity is associated with a receptor-level defect and internal changes in the insulin signaling pathway, without a significant alteration in the number of the GLUT-4 glucose transporter responsible for insulin sensitivity." (PMID 38655176, 2024). "The serum insulin concentrations at fasting, 1 h, 2 h and 3 h after OGTT in women of vitamin D group (obesity) were significantly lower than that in control group (obesity) (P = 0.041, P = 0.022, P = 0.030, P = 0.043)." (PMID 39014475, 2024). "Previous studies also showed that CVAI was a better obesity indicator for coronary heart disease incidence than VAI, WC, and BMI and for stroke than other insulin resistance indices." (PMID 38699393, 2024). "The etiology of obesity in PWS remains incompletely understood, with proposed mechanisms including insulin resistance, caloric imbalance, and hyperghrelinemia." (PMID 39135667, 2024). "The ability of insulin to regulate lipolysis, as reflected by a greater IC50 for suppression of palmitate release, was impaired in both leg and UBNS fat in those with obesity." (PMID 38602778, 2024). "Obesity influences HDAC expression levels and activities, leading to dysregulations in energy metabolic pathways, insulin sensitivity and adipogenesis." (PMID 39109269, 2024). "Altered adipokine profiles have been observed in obesity and T2DM, leading to severe metabolic risks and changes in insulin sensitivity." (PMID 39051061, 2024). "In participants with obesity, we observed significantly elevated inflammatory marker (TNF-α and IL-6), myeloperoxidase, leptin, and insulin levels (p < 0.05)." (PMID 39700087, 2024). "One RCT examined the effect of a lacto-ovo vegetarian dietary pattern, compared with a conventional diabetic diet, on fasting plasma insulin in adults with T2DM and overweight or obesity (n = 74)." (PMID 39415400, 2024). "The level of IPA can predict the occurrence of obesity, and IPA supplementation has been shown to improve blood glucose, increase insulin sensitivity, inhibit liver lipid synthesis and inflammatory factors." (PMID 38479983, 2024). "Adipose tissue hypoxia in obesity also reduces IR and IRS1 tyrosine autophosphorylation, directly affecting their ability to perceive insulin." (PMID 39692821, 2024). "After 8 weeks of intervention, the intervention group showed significant improvements in obesity indices (body weight, BMI, and PBF), lipid profiles (TG, TC, LDL-C, and HDL-C), FBS, insulin levels, and HOMA-IR and HOMA-B (p < 0.001)." (PMID 39080737, 2024).
Obesity (continued). "FABP4 has been identified as a regulator of islet function in obesity, where higher levels of FABP4 are documented in individuals with obesity and FABP4 was shown to elevate insulin secretion." (PMID 38961153, 2024). "Specifically, after 6 months of vitamin K2 supplementation, there were significant reductions in fasting serum glucose, insulin, and HbA1c levels in patients with T2DM and significant glucose tolerance improvement in diet-induced obesity mice." (PMID 38257161, 2024). "Concentrations of KIC in the range of ~15–20 μM have been reported in ob/ob mice and diet-induced obesity, while plasma KIC concentrations increased from ~12 to ~24 μM in insulin resistant obese Zucker rats compared to lean counterparts." (PMID 39163364, 2024). "We also included the IGI as a correlate for acute insulin response and ODI as an informative estimate of β-cell function in children and adolescents with obesity." (PMID 38087928, 2024). "The primary challenge lies in finding a delicate balance between intensified insulin therapy, necessary for glycemic control in T1DM, and achieving or maintaining an optimal weight to manage obesity." (PMID 39135667, 2024). "The study investigated the effects of various extracts on plasma levels of leptin, insulin, triiodothyronine (T3), thyroxine (T4), triglycerides, high-density lipoprotein (HDL), low-density lipoprotein (LDL) and lipase enzyme in obesity-induced rats." (PMID 39055496, 2024). "In one of the initial trials investigating GLP-1 RAs, 60 patients with obesity, T2DM, and MASLD were randomized to receive exenatide 10 μg twice daily versus insulin boluses." (PMID 39063598, 2024). "On the other hand, obesity can inhibit the synthesis of SHBG in the liver, thus promoting the secretion of androgen and insulin, which leads to IR, while high levels of insulin and androgen further aggravate the abnormal fat distribution." (PMID 36967808, 2023). "Genetically modified mice lacking PKC are leaner with greater oxygen consumption, resistant to obesity and steatosis put on by HFD, and have enhanced insulin sensitivity." (PMID 37237937, 2023). "Those diagnosed with obesity had higher levels of cholesterol, triglycerides, LDL-C, insulin, and HOMA-IR." (PMID 37887427, 2023). "Insulin levels in the infected groups were significantly decreased in the T1DM group and significantly increased in the obesity group." (PMID 37296126, 2023). "In the present study, females with obesity from both groups displayed a decrease in total cholesterol, LDL-c, triglycerides, fasting glucose, HbA1c, insulin, HOMA-IR, and an increase in HDL-cholesterol over the 1-year follow-up." (PMID 37591922, 2023). "In a multicenter ADOPT study, it was found that participants with LADA and T2D were similar in terms of overweight/obesity; nevertheless, those with LADA were more insulin resistant and tended to be obese, but leaner than individuals with T2D9." (PMID 37120620, 2023). "Studies in rodents revealed that ω3 PUFAs contributed to obesity phenotype improvements, including WAT inflammation, insulin sensitivity, glucose tolerance, and colonic inflammation, by targeting gut microbiota." (PMID 37755259, 2023). "Nowadays, obesity and IR are more prevalent among patients with T1DM because of modern lifestyle factors, chronic intensive subcutaneous insulin treatment, and other factors." (PMID 38111445, 2023). "Apart from age and sex, we record anthropometrics (blood pressure, heart rate, obesity), lifestyle (LTPA, smoking, alcohol), and biochemical measurements (irisin, lipid profile, insulin resistance)." (PMID 37448465, 2023). "The average disutility of once-daily versus once-weekly GLP-1 RA was − 0.048 in obesity and − 0.033 in T2DM; the corresponding average disutility for insulin was − 0.064." (PMID 35526173, 2023).
Obesity (continued). "While the effect of obesity and elevated BCS have been studied rather widely regarding reproductive success, essentially only a minority of the studies have evaluated the insulin status of the horses." (PMID 37152686, 2023). "In fact, S6K1 deficient mice have been found to be hypo-insulinemic and glucose intolerant, yet are insulin-sensitive and protected against HFD-induced obesity and hepatic steatosis." (PMID 37531359, 2023). "In murine models of obesity, hepatic p38 MAPK was activated and when p38 MAPK was overexpressed in the liver, it led to the impairment of insulin signaling." (PMID 36984693, 2023). "Lastly, insulin BBB transport is modified by many serum factors and in various diseases and conditions, including obesity, diabetes, AD, aging, and exercise." (PMID 37076875, 2023). "Another study highlighted the role of insulin signaling and the downstream HIF-1α-Med23-PPARγ-ST2 axis during VAT Treg development in the context of obesity and aging." (PMID 37197653, 2023). "Regarding the glycemic profile, notable differences were observed in insulin and HOMA-IR levels, which gradually widened between the groups with remitting, incident and stable obesity, reaching a maximum in the latter." (PMID 36639534, 2023). "Analogous urinary changes were presented in previous studies of Zucker obese rats, in rodent models with diet-induced obesity such as spontaneously hypertensive or Wistar Kyoto (WKY) rats and C57BL/6J mice, and in obese insulin-resistant humans." (PMID 37110210, 2023). "Subjects with obesity and NAFLD are less responsive to the action of insulin, and they exhibit increased lipolysis in subcutaneous and visceral fat resulting in increased free fatty acid (FAA) circulation." (PMID 37299398, 2023). "The identification of a simple neuronal circuit where dopamine-insulin signaling regulates feeding and growth could serve as a useful model for investigating new therapeutic strategies targeted towards the treatment of psychological disorders for obesity and metabolic syndrome." (PMID 37363909, 2023). "Further, loganin inhibited metabolic abnormalities, such as hepatic steatosis and adipocyte enlargement, and increased the serum levels of leptin and insulin in both OVX- and HFD-induced obesity models." (PMID 36902181, 2023). "In this context, the improved insulin and GH levels could be responsible for the increase in muscle lipid oxidation pathways and epigenetic regulation of muscle differentiation, as assessed from Gene Ontology analyses in people with obesity at 52 weeks after bariatric surgery." (PMID 36959287, 2023). "In conclusion, our study confirms that insulin-resistant patients with FPLD2 and obesity share common complications related to AT dysfunction." (PMID 37081489, 2023). "Studies performed in vitro using isolated human adipocytes have demonstrated that insulin upregulates its expression, suggesting a link between insulin resistance and SELENOS expression in obesity." (PMID 37895024, 2023). "In comparison to other groups, the mean ± SD of the fasting blood glucose (mg/dl) level, insulin (μU/L) level, and HOMA-IR index significantly increased in the obesity group (p < 0.05)." (PMID 36644444, 2023). "In insulin-resistant individuals, HSL activity is decreased, leading to an increase in fat storage and obesity." (PMID 37240215, 2023). "Similar findings of enhanced hepatic insulin signaling and inhibited PEPCK activity have been reported in previous studies following physical exercise in animal models of obesity or T2DM." (PMID 37689713, 2023). "We evaluated participants’ body weight, BMI, fasting blood glucose, fasting insulin, and HOMA-IR, as well as HbA1C in six studies that looked at the effects of FMT on weight and glycemic management in obesity and other metabolic disorders." (PMID 37511862, 2023).